IFNGR1 (interferon gamma receptor 1)
Diseases named in the same sentence as IFNGR1 in open-access papers (continued):
Sharing a sentence is not in itself a finding about the gene and the disease.
IFNGR1 also shares sentences with these, for which no sentence is quoted: hepatocellular carcinoma (4 papers); Autoimmunity (3); breast (3); hemophagocytic lymphohistiocytosis (3); histoplasmosis (3); hyper-IgE syndrome (3); osteomyelitis (3); candidiasis (2); Cardiovascular Disease (2); chronic granulomatous disease (2); common variable immunodeficiency (2); eosinophilia (2); haematopoietic disease (2); Kabuki syndrome (2); Listeria infection (2); Mendelian susceptibility to mycobacterial diseases (2); non-small cell lung carcinoma (2); skin infection (2); WHIM syndrome (2); adult onset immunodeficiency syndrome (1); allergic disease (1); allergic rhinitis (1); astrocytoma (1); Atrophy (1); autoimmune polyendocrinopathy-candidiasis-ectodermal dystrophy (1); autoinflammatory syndrome (1); Behçet's disease (1); biliary atresia (1); brain cancer (1); brain tumor (1).
A further 71 diseases each share a sentence with IFNGR1 in 1 paper.